RNU6-886P (RNA, U6 small nuclear 886, pseudogene)
Gene: Small nuclear RNA gene on chromosome 14 (37,434,469 to 37,434,573, reverse strand). Ensembl gene ENSG00000207046.
Homologues: Orthologues: chimpanzee U6 (99% identical), macaque U6 (91% identical). Paralogues in human: RNU6-1060P (90% identical), RNU6-15P (90% identical), RNU6-41P (90% identical), RNU6-10P (89% identical), RNU6-12P (89% identical), RNU6-13P (89% identical), RNU6-20P (89% identical), RNU6-31P (89% identical), RNU6-32P (89% identical), RNU6-1 (88% identical), RNU6-166P (88% identical), RNU6-17P (88% identical), and 1287 more.